CCL20 (C-C motif chemokine ligand 20)
Diseases named in the same sentence as CCL20 in open-access papers (continued):
Sharing a sentence is not in itself a finding about the gene and the disease.
cancer (continued). "Genes in response to interferon gamma, including CCL20, CCL25 and CD74, and antigen presentation-related genes, such as HLA-DPA1, HLA-DRA and HLA-DRB, were significantly upregulated in the cancer cells of immune-rich type tumors." (PMID 36729271, 2023). "It has been found that C-C motif chemokine ligand 20 (CCL20) is involved in the occurrence and development of various types of cancer." (PMID 36814485, 2023). "The CCL20/CCR6 axis has been shown to promote cancer progression through pro-angiogenic and immunosuppressive effects as well as through direct stimulation of cancer cell migration and proliferation." (PMID 36107259, 2022). "Some of these factors were exclusive to CAFs (mainly CXCL10 and CXCL12), others to cancer cells (mainly CXCL7 and CCL20), and some factors, such as CCL2, were common to both cell types." (PMID 35192545, 2022). "The chemokine CCL20 and its receptor CCR6 promotes cancer progression by increasing the proliferation and migration of cancer cells." (PMID 36226048, 2022). "This ligand has been found to enhance the migration and proliferation of cancer cells through the CCL20/CCR6 signaling pathway and to inhibit cell apoptosis, which directly promotes cancer progression." (PMID 35480896, 2022). "CCL20 and CA125 serum levels were significantly higher in the patients with cancer than in those with benign." (PMID 36387204, 2022). "For example, in a clinical study about ovarian cancer, the macrophages are activated after cisplatin chemotherapy, which increase CCL20 level and activate CCR6 of cancer cells to trigger EMT and reduce efficacy of chemotherapy." (PMID 35672862, 2022). "Out of the detected hub genes, six (CCL20, CXCL1, CXCL3, CXCL8, CXCL11, and MMP1) were among over-expressed vDEGs which have been corroborated by the GEPIA in both COAD and READ cancer types." (PMID 35333898, 2022). "With concerted, extensive efforts, the functional role played by the CCL20/CCR6 axis is gradually being unfolded, particularly in regulating cancer progression and metastasis within the TME." (PMID 35702353, 2022). "The study is the first systemic study that discloses the role of CCL20 in LUAD progression and cancer immunotherapy based on the maximum sample size." (PMID 35864953, 2022). "The CCL20/CCL6 axis is activated by chemotherapy with cisplatin, leading to increased cancer cell migration and EMT-based resistance." (PMID 34208465, 2021). "By analyzing three public cancer datasets, we found two intersection genes, SAA1 and CCL20, in these three datasets." (PMID 34084746, 2021). "CCL20 was the ligand of CCR6 and reported to be accountable for recruiting CD4+ T cells to promote STAT3 activation to foster cancer stemness." (PMID 33514440, 2021). "Cancer cells in Epstein-Barr virus (EBV) infection-positive Hodgkin's lymphoma patients can recruit Tregs by expressing the chemokine CCL20 via the EBV core antigen EBNA1, which allows cancer cells to evade immune surveillance." (PMID 34305476, 2021). "CCL20 recruits T cells to maintain the immunosuppressive environment and ensure cancer progression, while CCL6 can induce cancer cell migration and invasion." (PMID 34208465, 2021). "To investigate the mechanisms that altered migration and invasion of gastric cells, we evaluated the expression of cytokines CCL20, CCL28, and CXCL-2, which promote the migration and invasion of various cancer cells." (PMID 33194715, 2020). "While CCL14 and XCL1 have shown only good prognostic value, other chemokines such as CCL5, CCL20/CCR6, CCR7, CXCL1, CXCL8, and CXCL12/CXCR4 have consistently played the role of poor prognostic markers in different kinds of cancer." (PMID 31991604, 2020). "The CCL20/CCR6 network facilitates Treg activity and induces immune suppression to mediate cancer cell elimination and metastasis." (PMID 31991604, 2020). "However, the role of CCL20 may differ among cancer entities." (PMID 32601464, 2020).
cancer (continued). "The chemokines CCL20, CCL17, CCL22, RANTES, macrophage migration inhibitory factor (MIF), MCP1, and CCL4, secreted by cancer cells, fibroblasts, and dendritic and myeloid cells, were responsible for their recruitment to the tumor microenvironment." (PMID 32148497, 2020). "The present article highlighted the unique role of chemokine (C-C motif) ligand 20 (CCL20), which belongs to the CC chemokine family, and its specific receptor C-C chemokine receptor 6 (CCR6) in cancer progression." (PMID 32707869, 2020). "Firstly, the expression of CCL20 and IL-17A in CRC tissues was significantly higher than that in other cancer tissues." (PMID 31387598, 2019). "In order to investigate the function of CCL20 in TNBC, we silenced CCL20 in TNBC cell lines and found knockdown of CCL20 significantly decreased the proliferation of cancer cells." (PMID 30052635, 2018). "Hence, the CCR6/CCL20 axis was found to be engaged in the proliferation and migration of cancer cells via autocrine or paracrine mechanisms, and it was suggested that disruption of the functions of this chemokine duo may offer a promising strategy to treat cancers in the lung." (PMID 30453514, 2018). "Some genes are important factors in the immune system of cancer patients, such as CCL2, CCL20, CCL5, CCR7, IFNG and P450 family." (PMID 28384236, 2017). "The effect of IL-17RB on PDAC proliferation and dissemination was mediated by upregulation of CCL20, CXCL1, and IL-8 cytokines through ERK signaling in PDAC cancer cells." (PMID 29379802, 2017). "Furthermore, CCL20 could facilitate migration/invasion and promote cancer progression through EMT." (PMID 27015366, 2016). "It indicates that there is a direct link between the expression of IL-17, CCL20, telomerase, S100A8, and S100A9 in the fibrotic condition and the progression towards cancer." (PMID 26273651, 2015). "To confirm the role of CCL20 in autocrine stimulation of cancer cells from a different origin, we tested the expression of CCR6 in CCL20-secreting NB4, HL60, and HT-29 cells." (PMID 19340288, 2009). "As TNF-α enhances CCR6 expression, CCR6+ cells interact with CCL20, facilitating migration in cancer cells but not affecting normal thyroid cells." (PMID 40150133, 2025). "Additionally, they discovered that macrophages resembling MDSCs and TAMs increased levels of proteins that inhibit the immune system and promote cancer development, including SPP1, CCL20, and TIMP1." (PMID 40422244, 2025). "CCL20 was silenced using CCL20 siRNA in both Caki and MDA-MB-231 cancer cells." (PMID 38297161, 2024). "Therefore, CCL20, FBL, and PDK4 emerged as common biomarkers for IS and pan-cancer, crucial for predicting prognosis in patients with both conditions." (PMID 38914792, 2024). "Moreover, the promotion of chemokine CCL20 by Fusobacteria42 has been shown to work in axis with CC6 in oesophageal cancers to promote proliferation and migration, ultimately promoting cancer progression." (PMID 39674881, 2024). "Similarly, WO2017011559A1 (anti-CCL20 Abs) can bind to CCL20 and inhibit the interaction between CCR6 and CCL20, thereby mediating the inhibition of Treg/Th17 recruitment to the tumors, which can inhibit cancer stem cell activity and the tumorigenesis." (PMID 37936703, 2023). "MIP-3α/CCL20/promotes TAM migration, stimulating cancer cell proliferation." (PMID 37373025, 2023). "Cancer cells (i.e., CNA+) from the prepuberty disease state had significant high expression of genes involved in the innate immunity and chemokine signaling pathway (Ccl2, Ltf, Ccl7, Ccl20)." (PMID 35851387, 2022). "Overexpression of CCL20 overactivates the MAPK-PI3K signaling pathway, thus leading to high chemoresistance, accelerated proliferation, or a more stable ability to reside in new locations of cancer cells." (PMID 35480896, 2022).
cancer (continued). "Nevertheless, a recent study in CRC showed that cancer cells alone do not secrete CCL20 but require environmental factors for its production, suggesting that other populations cooperate with cancer cells for CCL20 synthesis." (PMID 33924428, 2021). "A direct coculture system of macrophage-like cells and SCC25 cells as a model of invasive cancer microenvironment promoted CCL20 secretion specifically, whereas the secretion of no other factors was confirmed." (PMID 34178651, 2021). "In addition, the CXCL12/CXCR4/CXCR7 and CCL20/CCR6 chemokine axes are known to promote migration and the invasiveness of cancer." (PMID 32775427, 2020). "However, the same chemokines recruit cells that promote the development of cancer, for example CCL17/TARC and CCL22/MDC, CCL20/LARC or CCL19/ELC and CCL21/SLC." (PMID 32781743, 2020). "Th17 lymphocytes, which are detected in malignant tumors, are characterized by increased expression of CXCR4 and CCR6 receptors, respectively, for the chemokine (C-X-C motif) ligand-12; CXCL12 (SDF-1α) and chemokine (C-C motif) ligand 20 (CCL20)." (PMID 32148497, 2020). "CCL20 is also overexpressed in many types of cancers, however its role in tumors is not fully explained." (PMID 31671654, 2019). "Then, we intraperitoneally administered either anti-human CCL20 antibody to target inoculated human cancer cell-derived CCL20 or anti-mouse CCL20 antibody to target surrounding non-cancer cell-derived CCL20 to the mice for 6 weeks." (PMID 28851919, 2017). "Phosphoinositide‐3‐kinase pathway is widely distributed and closely related to cytokine production and cancer development 21, although the involvement of the PI3K pathway on CCL20 production remains unclear." (PMID 26968871, 2016). "Cancer patients expressed higher mRNA levels of the M2 polarization markers CD163, ARG1 and IL-10 in CD11b+ cells and increased levels of the M2 cytokines IL-10 and CCL20 in plasma." (PMID 26840567, 2016). "Notably, CCL20 and CXCL16 mRNA were found to be more strongly expressed in cancer tissue than in unaffected tissue." (PMID 27517754, 2016). "Our data supported the hypothesis that CCL20 was elevated in RANKL-treated RANK over-expressed EC cells, and then contributed to immune suppression-mediated cancer cells metastasis via EMT." (PMID 27015366, 2016). "Therefore, there is a direct link between the expression of IL-17, CCL20, telomerase, S100A8, and S100A9 in the fibrotic condition and the progression towards cancer." (PMID 26273651, 2015). "Our data suggest that activation of the CCL20/CCR6/IL-17 axis is also detectable in the histologically normal mucosa of smokers with cancer of the respiratory tract." (PMID 24497500, 2014). "Furthermore, our data suggest a role of the chemokine CCL20 in CXCR4-dependent and independent regulation of cancer growth and point to CCR6 and CCL20 as novel therapeutic targets in cancer." (PMID 19340288, 2009). "Furthermore, our data suggest an in vivo role of the chemokine CCL20 in CXCR4 dependent and independent regulation of cancer growth and point to CCR6 and CCL20 as novel therapeutic targets in cancer." (PMID 19340288, 2009). "Here we show that, CCL20 promotes the growth and adhesion of CCR6-expressing cancer cell lines." (PMID 19340288, 2009). "Besides, whether the SIK1/PI3K/AKT and CCL20/CCR6 signaling pathways for miR-183-5p are specific in HCC and whether the axis has an effect on angiogenesis in other cancers remain questions that need to be explored." (PMID 40115013, 2025). "Therefore, the increased expression of IL6 and CCL20 in response to AFB1 may play a role in AFB1-related inflammatory diseases and cancers." (PMID 38468450, 2024). "It is also possible that inflammatory mediators‐induced overproduction of CCL20 from NSCLC cells and other cells may increase the resistance of cancer cells to therapies, the metathesis of cancer cells or the cell capability of residing or survival even in the new location." (PMID 26968871, 2016).
cancer (continued). "The in vivo role of CCL20 in cancer development is not clear." (PMID 19340288, 2009). "However, the role of CCL20 in cancers has not been well elucidated." (PMID 30052635, 2018). "Because injections of CCL3 and CCL20 did not induce any detectable inflammatory response or liver injury in vivo (data not shown), we believe it is possible that CCL3 and CCL20 could be employed to efficiently recruit DC precursors for the purpose of DC-based cancer therapy." (PMID 20420712, 2010). "Although the development of drugs modulating the CCL20/CCR6 axis is expected but currently not available, blocking the CCL20–CCR6 axis in combination with standard cancer therapies has shown promising results." (PMID 39985603, 2025). "In addition, we tested whether the gain-of-function of CCL20 in the Cat D KO cancer cells, CD204+ TAM polarization, and Cox2 and Arg1 expression were rescued in TAMs primed by CCL20 overexpression in the Cat D KO cancer cells compared with those of TAMs primed by the Cat D KO cancer cells." (PMID 38297161, 2024). "Serum concentrations of CCL20 and LCN2 were remarkably elevated in cancer groups in comparison with noncancer groups." (PMID 35308139, 2022). "As already described for CCL20, NF-κB-driven CX3CL1 expression had no direct effects on cancer cell apoptosis or proliferation." (PMID 31561620, 2019). "Several genes were also, however, inconsistent with the mouse model data including CCL5, CCL20, CCL22, CCL28, CXCL10, and PDL2, suggesting that these features may not be as robustly tissue-specific across different primary cancers." (PMID 33985562, 2021).
infection (237 papers, 2007 to 2026). The state of being infected such as from the introduction of a foreign agent such as serum, vaccine, antigenic substance or organism. "Infection elicits an inflammatory response and dysregulates genes associated with the innate immune system (CCL20, CD38, LCN2 and NR4A3)." (PMID 39666439, 2025). "Genes encoding β-chemokines (such as CCL20, which was upregulated at all three time points) participate in early immuno-protection against mycobacterial pathogens following infection." (PMID 22384131, 2012). "Furthermore, significantly reduced IL-6, CCL20, and hBD2 expression along with CXCL8 and CCL20 secretion by RHE were observed at 16 h post-infection using T3SS deficient strain." (PMID 30070169, 2018). "However, it is critical to have a “guardian”, in this case IL-22, to prevent overproduction of CCL20 during the late phase of infection leading to tissue damages caused by amplified inflammatory responses." (PMID 24824519, 2014). "This conclusion is supported, at least in part, by the results of Sukumaran and colleagues, who reported the upregulated expression of chemokine genes encoding CXCL1, CXCL2, CXCL3, CXCL8, CCL3, CCL4 and CCL20 after infection of PMN with Anaplasma phagocytophilum." (PMID 17875202, 2007). "All infections resulted in the expression of genes encoding the cytokine TNF-α, and the chemokine CCL20 in J774A.1 macrophages, with significant differences (p < 0.05) in transcription patterns compared to non-infected cells." (PMID 40727705, 2025). "CCL20 is a proinflammatory chemokine that primarily attracts T cells and dendritic cells to sites of infection and inflammation." (PMID 40867589, 2025). "Pigs infected with the HP-PRRSV isolate NA01/2024 in Vietnam showed upregulation of CCL20 in both whole blood and tissues, suggesting a potential role in the regulation and interaction of Th17, Treg, and B cells in response to infection." (PMID 41295722, 2025). "We also found weak evidence for a slight increase in CCL20 during infection (median fold change of 1.12 [95% CrI from 0.93 to 1.37]) and a slight decrease in IFNγ (median fold change of 0.85 [95% CrI from 0.55 to 1.24])." (PMID 39836629, 2025). "The chemokines (CCL2, CXCL1, CXCL8, and CCL20) facilitate the recruitment of monocytes and neutrophils to the site of infection." (PMID 40570043, 2025). "These recruited T cells, already expressing Ccr6, likely respond to CCL20 gradients to migrate to the site of infection." (PMID 40127923, 2025). "In contrast, Ccl20 mRNA expression was significantly increased during infection, and Brunner cells, enterocytes, goblet cells, and tuft cells were the major producers of CCL20." (PMID 40127923, 2025). "We selected five cytokines, including CXCL-1, CXCL-2, IL-6, IL-8, and CCL-20, and determined their expression levels 24 h after infection using qPCR." (PMID 38756230, 2024). "The expression levels of CXCL1, CCL17, and CCL20 were significantly upregulated 21 days after infection with the cdh1Δ mutant strain, indicating a pronounced activation of lung tissue recruitment of neutrophils and enhanced Th2 and Th17 immune responses." (PMID 39728387, 2024). "Similar results were observed in the neonatal murine model of C. parvum infection, with the highest diminution of CCL20 in the intestine at the peak of infection, but maintained at a lower amplitude in the later stages of the infection." (PMID 38756777, 2024). "These ILC3s were also found to strongly upregulate the expression of chemokine (C-C motif) ligand 20 (CCL20) in lung tissues during infection." (PMID 38391948, 2024). "Expression of IL-6, IL-8 (CXCL8), CXCL1, CXCL2, and CCL-20, which are known to be expressed in the respiratory epithelium upon infection, was assessed." (PMID 38756230, 2024). "In the intestine of lambs, CCL20 expression is also significantly reduced at the peak of infection and corroborates the observation in the mouse model of infection." (PMID 38756777, 2024).